LLPH (LLP homolog, long-term synaptic facilitation factor)
Description:
In hippocampal neurons, regulates dendritic and spine growth and synaptic transmission.
Synonyms: C12orf31; MGC14817; hLLP
Tractability: Small molecule: a structure with a bound ligand is known. PROTAC: UniProt records ubiquitination sites on it; ubiquitination databases record sites on it; its protein half-life has been measured.
Gene: Protein-coding gene on chromosome 12 (66,116,555 to 66,130,750, reverse strand). Ensembl gene ENSG00000139233.
Subcellular location: Nucleus, nucleolus; Chromosome
Subcellular location (Human Protein Atlas): Nucleoli; Mitotic chromosome
Gene Ontology:
Molecular function: protein binding; RNA binding
Biological process: dendrite extension; positive regulation of dendritic spine development
Cellular component: chromosome; nucleolus
Genetic constraint (gnomAD): Loss-of-function variants: 4 observed, 8.5 expected, observed/expected ratio (o/e) 0.47, 90% interval 0.23 to 1.08. That is too few expected variants to judge how well the gene tolerates losing a copy. Missense variants: 101 observed, 110.91 expected, observed/expected ratio (o/e) 0.91, 90% interval 0.77 to 1.07. Synonymous variants: 26 observed, 34.65 expected, observed/expected ratio (o/e) 0.75, 90% interval 0.55 to 1.04.
Homologues: Orthologues: chimpanzee LLPH (100% identical), macaque LLPH (97% identical), rabbit LLPH (90% identical), dog LLPH (89% identical), pig LLPH (88% identical), rat Llph-ps1 (85% identical), guinea pig LLPH (82% identical), mouse Llph (81% identical).
Diseases named in the same sentence as LLPH in open-access papers:
LLPH is named in the same sentence as 3 diseases in open-access papers, as found by Europe PMC text mining. Sharing a sentence is not in itself a finding about the gene and the disease. The quoted sentences say what the papers report.
cancer (1 paper, 2025). A tumor composed of atypical neoplastic, often pleomorphic cells that invade other tissues. "We also find that we are able to successfully transfer our cancer models to tumour-adjacent tissue when inspecting the top 6 genes explained by CNVs (i.e. LLPH, YEATS4, UQCRFS1, POP4, CNOT2, and CAND1)." (PMID 40041206, 2025).
LLPH also shares sentences with these, for which no sentence is quoted: mental disorder (1 paper); tumour (1).